AR (androgen receptor)
Diseases named in the same sentence as AR in open-access papers (continued):
Sharing a sentence is not in itself a finding about the gene and the disease.
male infertility (47 papers, 2012 to 2025). The inability of the male to effect fertilization of an ovum after a specified period of unprotected intercourse. "Previous studies have shown that high expression of Efcab6 in cells can inhibit transactivation of AR, thereby suppressing AR expression and ultimately causing male infertility." (PMID 40643461, 2025). "Changes in the androgen receptor (AR) and its expressed proteins are among the causes of impaired spermatogenesis and idiopathic male infertility, as the AR plays a key role in androgen action." (PMID 40075943, 2025). "Many authors have shown that “long” CAG repeats of the AR gene increase the risk of impaired spermatogenesis and male infertility in different populations and regions." (PMID 39596257, 2024). "In conclusion, we found evidence of an association between novel polymorphisms of AR and ER-α and male infertility among the Iranian population." (PMID 35958962, 2022). "The search for the causes of male infertility allowed for identifying a number of genetic factors including a single X-linked gene of the androgen receptor (AR), and some of its alleles are assumed to negatively affect male fertility." (PMID 36142533, 2022). "Due to the fundamental effects of AR in spermatogenesis, various gene polymorphisms of AR concerning male infertility have been studied." (PMID 35958962, 2022). "Similar to AR, it is suggested to conduct more observational studies to elucidate the association between different types of ER-α genotypes with male infertility." (PMID 35958962, 2022). "Most meta-analysis studies have concluded that the increase in CAG repeat length in AR is associated with male infertility." (PMID 35958962, 2022). "The present case-control study, therefore, examined the association of different polymorphisms of AR and ER-α genes with male infertility among the Iranian population." (PMID 35958962, 2022). "In terms of AR rs137852599, there was a significant association between the C allele (recessive allele) and odds of male infertility compared with the dominant allele (OR: 0.545, CI: 0.304-0.978)." (PMID 35958962, 2022). "We found for the first time, an inverse association between AR rs1378525568 TT genotype and AR rs137852599 C allele with male infertility." (PMID 35958962, 2022). "Heterozygote overdominance was also observed in ESR rs796065354 but not in the other variants studied.Conclusion: Pieces of evidence were found on the association of novel polymorphisms of AR and ER-α with male infertility among the Iranian population." (PMID 35958962, 2022). "Pathogenic variants in FKBPL cause male infertility by disrupting the androgen receptor (AR) signal." (PMID 34212559, 2021). "Apart from AR, additional X-chromosomal genes have been postulated to be causative for male infertility, including TEX11, MAGEB4, RHOX and TAF7L." (PMID 31875237, 2021). "The androgen receptor (AR) remains the best studied X-linked gene so far in the etiology of male infertility." (PMID 31875237, 2021). "Our findings revealed that the risk of male infertility increased with elevating the length of androgen receptor-CAG trinucleotide repeat." (PMID 30713477, 2018). "Numerous studies have been performed to determine the association between the length of CAG repeats in the AR gene and male infertility." (PMID 30713477, 2018). "The subgroup study on races shows that increased AR-CAG repeat length was associated with male infertility in Asian, Caucasian, and mixed races." (PMID 26962784, 2016). "This meta-analysis supports that increased androgen receptor CAG length is capable of causing male infertility susceptibility." (PMID 26962784, 2016). "Reports on association between male infertility and gene polymorphism of androgen receptor mostly focused on Caucasian race and Asian race." (PMID 26962784, 2016).
male infertility (continued). "Some studies demonstrated that longer length of AR-CAG trinucleotide repeats was associated with increased risk of male infertility, which is typical of impaired spermatogenesis with different severity." (PMID 26962784, 2016). "Specific knock out of AR in Sertoli or Leydig cells caused male infertility with spermatogenic arrest and hypotestosteronemia." (PMID 25255222, 2014). "It depends on an X-linked mutations in the Androgen Receptor (AR) gene that express a variety of phenotypes ranging from male infertility to completely normal female external genitalia." (PMID 23533861, 2013). "The role of AR CAG polymorphism in male infertility was also clarified in a later meta-analysis." (PMID 36142533, 2022). "It was noted that the association of long AR CAG alleles with male infertility or poor semen quality was confidently established for populations of the Caucasian race, but such associations were rare in Asian and African populations, which was confirmed by the conclusions of several meta-analyses." (PMID 36142533, 2022). "Population studies have revealed not only genetic differences in the frequencies of alleles of the CAG polymorphism of the AR gene between races or ethnicities, but also associated reproductive differences, including male infertility, impaired spermatogenesis and diseases of the reproductive system." (PMID 36142533, 2022). "Besides, the length of the polymorphic CAG repeat encoding a polyglutamine stretch (8–35 in length) in the AR N-terminal transactivation domain has been linked to male infertility." (PMID 31875237, 2021). "Therefore, androgen receptor gene mutations can lead to several deleterious disorders, including male infertility." (PMID 30713477, 2018). "The overall study shows that increased AR-CAG repeat length was associated with male infertility." (PMID 26962784, 2016). "Numerous studies in recent years have attempted to establish the relationship between CAG repeat length variation and male infertility to find out if this variability in the AR gene could be associated with impaired spermatogenesis." (PMID 26421011, 2015). "Therefore, in humans, aberrant androgens or AR actions are associated with multiple pathologies, such as androgen insensitivity syndromes, prostate cancer, testicular feminization, and male infertility." (PMID 26690413, 2015). "Androgen receptor polymorphisms/mutations and endemic stress generated by fluctuating peripheral prolactin levels, prevalent across the globe are potential causes for the occurrence of chromatin condensation defects associated with male infertility." (PMID 23241214, 2012). "Thus, AR mutations can be considered a rare cause of male infertility." (PMID 31875237, 2021). "Additionally, androgen receptor (AR) mutations have been related to male infertility issues." (PMID 33924000, 2021). "Additionally, our meta-analysis suggests that AR-CAG repeat polymorphism has a relationship with male infertility, but the exact molecular mechanisms of how the CAG repeat polymorphism affects male infertility are unknown." (PMID 26962784, 2016). "Mice that lack the androgen receptor fail to receive androgens, leading to meiotic arrest and male infertility." (PMID 40391511, 2025). "Although the Y chromosome contains genetic material for male development, thereare multiple genes on the X chromosome involved with male infertility, the mostsignificant of which result in abnormalities and conditions related to theandrogen receptor (AR) gene." (PMID 36197143, 2022). "Several meta-analyses have reported the association between AR gene CAG repeat length polymorphisms and male infertility." (PMID 35958962, 2022). "Increased CAG length in the AR gene has been correlated with male infertility owing to a decreased transcription of the AR gene and diminished spermatogenesis." (PMID 36945970, 2022).
male infertility (continued). "The association between the AR-CAG repeat and male infertility has been intensively studied, but effects seem to be small and are still debated." (PMID 31875237, 2021). "The frequencies of the most common genetic abnormalities associated with male infertility are as follows: chromosomal abnormalities 5–7%, Y-chromosome deletions 5–10%, CFTR gene mutations 5%, AR mutations 2–3%." (PMID 34290736, 2021). "The meta-analysis showed a significant association between androgen receptor-CAG length and male infertility." (PMID 30713477, 2018). "In the current research, we evaluated the possible role of androgen receptor-CAG trinucleotide repeat length in idiopathic male infertility through a case-control followed by a meta-analysis." (PMID 30713477, 2018). "According to the results, a significant association was observed between increased length of AR-CAG polymorphism and male infertility (p< 0.0001)." (PMID 30713477, 2018). "Considering that Trf has been identified as an androgen receptor–dependent gene, it will be interesting to further explore in future pathologies related to male infertility that reflect a similar Trf expression pattern." (PMID 29047395, 2017). "Based on studies on association between AR-CAG repeat length and male infertility in recent years, an updated meta-analysis is needed." (PMID 26962784, 2016). "The association between polymorphism of androgen receptor gene CAG (AR-CAG) and male infertility in several studies was controversial." (PMID 26962784, 2016). "We aimed to evaluate the association between AR-CAG repeat length and male infertility in advantage of the data in all published reports." (PMID 26962784, 2016). "Our analysis suggests that further exploration of the molecular mechanism of AR-CAG repeat polymorphism and risk male infertility is demanded." (PMID 26962784, 2016). "There are many studies on AR gene as a responsible factor for spermatogenesis failure, but the role of polymorphic repeats in male infertility is unclear." (PMID 26221130, 2015). "Several polymorphisms have been shown to correlate with specific types of male infertility, including polymorphisms in the number of CAG repeats in exon 1 of the androgen receptor (AR), FSHR, estrogen receptor (ER) α, and gr/gr deletions in the AZFc gene." (PMID 25653674, 2015). "The goal of this study was to investigate any relationship between GGN repeat length in the first exon of AR gene and idiopathic male infertility in southwest of Iran." (PMID 26221130, 2015). "Mild defects in AR function are one of the genetic causes of impaired spermatogenesis and male infertility with no undermasculinization." (PMID 39596257, 2024). "This study aimed to explore the structural interactions of commonly used class II pyrethroids—cypermethrin and deltamethrin—with AR for potential disruption activity, which subsequently could lead to male infertility." (PMID 37187621, 2023). "Taken together, the results of this study suggested potential disruption of AR signaling by cypermethrin and deltamethrin, which may result in androgen dysfunction and subsequent male infertility." (PMID 37187621, 2023). "The exact mechanisms through which AR and ER-α polymorphisms influence male infertility risk are complex and not well-established." (PMID 35958962, 2022). "In addition to the AR gene, various X chromosome related genes have also beenimplicated in male infertility (TEX11, MAGEB4, RHOX, HAUS7, andTAF7L)." (PMID 36197143, 2022). "Some authors acknowledge that genotyping of the AR CAG repeat polymorphism currently has low diagnostic value due to the lack of clearly defined thresholds assessing the risk of male infertility." (PMID 36142533, 2022). "However, larger studies are warranted to confirm our findings.Key words:Male infertility, Androgen receptor, Estrogen receptor-α." (PMID 35958962, 2022).
male infertility (continued). "Longer AR CAG repeat lengths cause decreased sperm motility, corresponding to a greater severity of spermatogenic defect that can lead to disturbance in reproductive functions, thus causing male infertility." (PMID 36945970, 2022). "The genetic causes underlying male infertility include Y chromosome microdeletions, sex chromosome aneuploidies such as Klinefelter’s Syndrome, and gene polymorphisms such as those in LOC203413 or CAG repeats in androgen receptor gene." (PMID 36945970, 2022). "In the results, the Leydig cells staining and AR-positive germ cell staining were significantly reduced at HD compared to the control, which may indicate male infertility." (PMID 32053938, 2020). "Our results elucidated that long stretches of CAG repeat might lead to AR dysfunction, contributing to male infertility especially in the Caucasian population." (PMID 30713477, 2018). "Therefore, future studies with larger sample size in this area are needed to verify the association between AR-CAG repeat length and male infertility." (PMID 26962784, 2016). "A probable AR specificity further increases ES’ impact by its testes centric action and this damage further lead to qualitative and quantitative defects in spermatogenesis and results in male infertility." (PMID 27551453, 2015). "Additionally, some studies have suggested that AR variations may also be related to isolated male infertility." (PMID 41327353, 2025). "Given the role of AR and ER-α in spermatogenesis and male infertility, one might assume that binding of the AR-androgen complex to HSPs and the subsequent transfer of the complex to the nucleolus modify the transcription of various genes involved in spermatogenesis." (PMID 35958962, 2022). "Other proteins that interact with filamin A, include the AR and nephrocystin 4 (NPHP4) and we found in HF conditions, a significant decrease in filamin interacting protein NPHP4, important for cytoskeleton signalling, cell adhesion and ciliary development and associated with human male infertility." (PMID 32678325, 2020). "USP26/AR expression and interaction in spermatogenesis and androgen-dependent cancer warrants additional study and may prove useful in diagnosis and management of male infertility." (PMID 24922532, 2014). "Moreover, the CAG repeats in the AR gene is a polymorphism that may be associated (not a causal effect) with male infertility, and its clinical relevance is still debated." (PMID 36945970, 2022). "Whether AR-CAG trinucleotide repeats is linked to male infertility has not been fully revealed." (PMID 26962784, 2016). "The impact of AR function on male infertility was also strengthened by a finding of decreased immunohistochemical AR expression in testicular tissue of men affected by non-obstructive azoospermia (NOA)." (PMID 41595460, 2025). "The correlation between male infertility and CAG repeat lengths on the AR gene is still unknown, while the link between this polymorphism and quality of spermatogenesis is even more obscure." (PMID 26421011, 2015). "AR knockout (ARKO) mice display a complete insensitivity to androgens and male infertility; however, the exact molecular mechanism for this effect remains unclear." (PMID 26690413, 2015).
renal cell carcinoma (45 papers, 2015 to 2026). "In contrast, two other studies found that increased expression of AR mRNA was associated with poor prognosis in renal cell carcinoma." (PMID 41486951, 2026). "In breast, urothelial, and renal cell carcinomas, detectable AR staining was associated with favorable histopathological and clinical features." (PMID 38790919, 2024). "Given the tendency towards adjuvant therapy in high-risk renal cell carcinomas and the corresponding need for risk assessment in these tumors, AR might deserve further evaluation as a potential clinically useful prognostic marker in these tumors." (PMID 38790919, 2024). "Notably, a recent study reported that AR binds the DHX9 promoter in renal cell carcinoma and that this event is associated with osteolytic formation and bone metastasis, suggesting the possibility of a crosstalk between AR and DHX9." (PMID 35590370, 2022). "C1QBP regulates YBX1 and suppresses androgen receptor (AR)-enhanced invasion of renal cell carcinoma cells." (PMID 40799245, 2025). "In renal cell carcinoma, androgen receptor mediated CXCL5 signaling activates the AKT/NF-κB pathway to facilitate angiogenesis." (PMID 38343536, 2024). "HOTAIR, expressed at high levels, interacts with the androgen receptor (AR) in renal cell carcinoma and cooperatively promotes GLI2 transcription by binding to its promoter." (PMID 39280246, 2024). "Again, the lncRNA HOTAIR plays a role in estrogen and androgen receptor signaling and is regulated by estrogen receptor β in renal cell carcinoma." (PMID 38095719, 2024). "The role of androgen receptor (AR) in renal cell carcinoma is unclear– data suggests that the presence of AR is protective in RCC, while other studies indicate that increased AR expression is associated with increased proliferation and tumor stage." (PMID 38892327, 2024). "For example, LncRNA SARCC (Suppressing Androgen Receptor in Renal Cell Carcinoma) acts as ceRNA to isolate Mir-143-3p expression." (PMID 35069912, 2022). "Correspondingly, the novel long non-coding RNA lncRNA-SARCC (lncRNA-suppressing androgen receptor in renal cell carcinoma) has been shown to inhibit the AR protein by binding to it and destabilizing it, thus increasing the miR-143-3p level in RCC." (PMID 35163477, 2022). "The incidence of renal cell carcinoma is higher in males than in females due to the different androgen receptor signaling but the molecular mechanisms behind this gender bias are unclear." (PMID 29030639, 2017). "In this study, we systematically examined the expression of androgen receptor (AR) in RCCs and took advantage of a large hospital-based series of renal cell carcinomas with long-term follow-up information." (PMID 29108248, 2017). "Several studies showed loss of AR in renal cell carcinoma (RCC) in conjunction with increasing clinical stage and pathological grade, but others found that higher AR expression correlated with worse outcomes." (PMID 26814892, 2016). "In renal cancer, the lncRNA Suppressing Androgen Receptor in Renal Cell Carcinoma (SARCC) suppresses tumor growth by inhibiting androgen receptor functions, specifically through stabilizing the androgen receptor protein in males, leading to a repression of miR-142-3p." (PMID 38095719, 2024). "It has been reported that the androgen receptor could induce renal cell carcinoma initiation, progression, and invasion, which may explain why men are more likely to develop renal cancer than women." (PMID 38095719, 2024). "Early studies indicated that the androgen receptor (AR) could promote renal cell carcinoma (RCC) development and metastasis, but its linkage to RCC progression under hypoxia, remains unclear." (PMID 36397101, 2022). "Androgen receptor plays key roles in development of renal cell carcinoma." (PMID 32185172, 2020).